HRK (harakiri, BCL2 interacting protein)
Diseases named in the same sentence as HRK in open-access papers (continued):
Sharing a sentence is not in itself a finding about the gene and the disease.
tumor (20 papers, 2012 to 2025). "Yes-associated protein (YAP) causes tumor invasion and chemoresistance through inhibition of HRK expression in neuroblastoma." (PMID 36568155, 2022). "To validate these findings, we performed Western blotting analysis on tumor tissues from Group A and Group D. Consistent with sequencing data, HRK protein levels were elevated in Group D relative to Group A, while ARC expression was significantly reduced." (PMID 41334581, 2025). "In contrast, the expression of anti-apoptotic genes, such as HRK, and genes within the WNT and RAS signaling pathways, which are associated with tumor promotion, was substantially reduced (FDR < 0.05)." (PMID 41022704, 2025). "On the other hand, HRK in glioblastoma, non-small lung cancer, breast cancer as well as ovarian cancer inhibits tumor proliferation by promoting apoptosis." (PMID 36568155, 2022). "As a member of the pro-apoptotic subgroup of BCL-2 family, HRK is an essential initiators of apoptosis that can function as tumor suppressors." (PMID 34174847, 2021). "This phenotype can be blocked by forced expression of Bcl-2 and Bcl-xL, suggesting the functional interaction of Bcl-2/Bcl-xL and HRK in tumor cells." (PMID 30774992, 2019). "To examine the HRK expression effect on tumor growth in vivo, we first generated firefly luciferase (Fluc) and mCherry expressing U87MG GBM cells by transducing GBM cells with Fluc-mCherry expressing viral vectors (FMC)." (PMID 30774992, 2019). "Effect of the HRK overexpression on tumor growth was also tested in orthotropic in vivo model of GBM, where U87MG-FMC cells were intracranially injected." (PMID 30774992, 2019). "Few studies show the suppressed expression levels of HRK in tumors by methylation and exogenous expression of HRK attenuates tumor growth in some cancers." (PMID 30774992, 2019). "By employing gain-of- and loss-of-function approaches, we showed that HRK overexpression induces apoptosis in different GBM cells at different levels and attenuates tumor growth in vivo." (PMID 30774992, 2019). "Subcutaneous injection of the cells in immunocompromised mice and long-term analysis of tumor growth revealed that HRK expression attenuates tumor growth in vivo." (PMID 30774992, 2019). "In the tumor tissues, immunofluorescence staining showed that HRK-expressing tumors were smaller in volume, had less vascularity as shown by Laminin staining, and less Ki-67 proliferation index compared to control tumors." (PMID 30774992, 2019). "Abnormal methylation of HRK promoter prevented binding of AP-2α and resulted in down regulation of HRK expression, which was followed by resistance to apoptosis and enhanced tumor growth." (PMID 27478805, 2016). "Finally, we showed that HRK expression led to slower tumor growth in subcutaneous and orthotopic tumor models in vivo." (PMID 30774992, 2019). "As tumor cells’ apoptotic response might be correlated with the endogenous levels of apoptotic family members, we examined HRK expression levels in a panel of established GBM cell lines (A172, LN18, U87MG, and U373)." (PMID 30774992, 2019). "Finally, we showed that HRK induction suppresses tumor growth in orthotopic GBM models in vivo, leading to increased survival." (PMID 30774992, 2019). "Also, we showed that HRK-induced apoptosis could be inhibited by forced expression of Bcl-2 and Bcl-xL, suggesting the functional interaction of Bcl-2/Bcl-xL and HRK in tumor cells." (PMID 30774992, 2019). "Consistently with transcriptomic analysis, we also observed marked differences in the mRNA levels of BAX, HRK, CDK6, CDK14, and BCL2 between the sgCONT and NOXAKO tumor cells after co-incubated with CD19 CAR T cells." (PMID 35370290, 2022). "Upregulation of anti-apoptotic genes, including BAG1, BCL11B and SERPINB2, and downregulation of apoptotic genes, such as DAPK2, HRK and TP53INP1, can promote tumor cell survival." (PMID 23024765, 2012).
tumor (continued). "In patient-derived cell lines, we did not observe a clear trend in BCL2L1 (BCL-xL gene) nor HRK mRNAs, probably due to higher inter-tumor variability compared to the MCL-1:NOXA adaptation." (PMID 40113795, 2025). "Moreover, HRK overexpression cooperates with tumor necrosis factor-related apoptosis-inducing ligand (TRAIL), a known tumor-specific pro-apoptotic agent." (PMID 30774992, 2019). "Aberrant methylation is a specific characteristic of HRK in various tumor cells that is not seen in other BH3- only family genes (BAD, BID, and PUMA) examined." (PMID 27478805, 2016). "Since LN18 and U87MG cells are both responsive to HRK overexpression and TRAIL treatment, they might be categorized under Type II cells and the apoptotic mechanisms regulated by HRK in such tumor cell types might be different than that of A172 cell like Type I cells." (PMID 30774992, 2019).
HRK also shares sentences with these, for which no sentence is quoted: lung carcinoma (2 papers); astrocytic tumor (1); bladder cancer (1); chondrosarcoma (1); Glucose intolerance (1); gonococcal infection (1); leukemia (1); liver cancer (1); medulloblastoma (1); myelodysplastic syndrome (1); nasopharyngeal carcinoma (1); pancreatitis (1); primary brain tumor (1); skin disorder (1); squamous cell carcinoma (1).